CFAP100 (cilia and flagella associated protein 100)
Description:
Microtubule-associated protein that promotes microtubule polymerization and regulates microtubule organization. Plays a critical role in ensuring proper epidermal development and function by regulating mitosis in keratinocytes. Maintains spindle pole integrity during keratinocyte division through the recruitment of the microtubule glutamylase TTLL13 to spindle poles, thereby enhancing localized microtubule glutamylation. This modification stabilizes spindle microtubules, ensuring accurate spindle assembly, faithful chromosome segregation, and efficient mitotic progression. May play a role in ciliary/flagellar motility by regulating the assembly and the activity of axonemal inner dynein arm.
Synonyms: CCDC37; FLJ40083; MIA1
Tractability: Small molecule: a structure with a bound ligand is known. PROTAC: ubiquitination databases record sites on it.
Gene: Protein-coding gene on chromosome 3 (126,394,656 to 126,436,556, forward strand). Ensembl gene ENSG00000163885.
Subcellular location: Cytoplasm, cytoskeleton, cilium axoneme; Cytoplasm, cytoskeleton, spindle pole; Cytoplasm, cytoskeleton
Subcellular location (Human Protein Atlas): Mid piece; Principal piece
Gene Ontology:
Molecular function: microtubule binding; protein binding; dynein complex binding
Biological process: chromosome segregation; keratinocyte proliferation; microtubule cytoskeleton organization; microtubule polymerization; mitotic spindle organization; cilium movement; inner dynein arm assembly; skin epidermis development
Cellular component: ciliary basal body; microtubule; spindle pole; axonemal doublet microtubule; motile cilium; axoneme; cytoskeleton
Genetic constraint (gnomAD): Loss-of-function variants: 65 observed, 76.73 expected, observed/expected ratio (o/e) 0.85, 90% interval 0.69 to 1.04. The upper end of that interval is the gene's LOEUF score, 1.04, which puts it in group 4 of 6, group 1 being the genes least tolerant of losing a copy. Missense variants: 786 observed, 761.34 expected, observed/expected ratio (o/e) 1.03, 90% interval 0.97 to 1.1. Synonymous variants: 332 observed, 313.65 expected, observed/expected ratio (o/e) 1.06, 90% interval 0.97 to 1.16.
Homologues: Orthologues: chimpanzee CFAP100 (99% identical), macaque CFAP100 (92% identical), dog CFAP100 (74% identical), pig CFAP100 (67% identical), rat Cfap100 (65% identical), mouse Cfap100 (64% identical), guinea pig CFAP100 (58% identical), tropical clawed frog cfap100 (42% identical), zebrafish cfap100 (36% identical). Paralogues in human: CCDC38 (29% identical), CCDC42 (11% identical), CFAP73 (9% identical).
Diseases named in the same sentence as CFAP100 in open-access papers:
CFAP100 is named in the same sentence as 5 diseases in open-access papers, as found by Europe PMC text mining. Sharing a sentence is not in itself a finding about the gene and the disease. The quoted sentences say what the papers report.
ciliopathy (1 paper, 2025). A genetic disorder of the cellular cilia or the cilia anchoring structures, the basal bodies, or of ciliary function. "For the other two IDA-related genes (Acta2, Cfap100/Ccdc37) and one RS-related gene (Morn3), no ciliopathy has been linked to mutations of these three genes so far." (PMID 40568142, 2025).
CFAP100 also shares sentences with these, for which no sentence is quoted: ovarian carcinoma (2 papers); glioma (1); lung carcinoma (1); lung squamous cell carcinoma (1).